CD79B (CD79b molecule)
Diseases named in the same sentence as CD79B in open-access papers (continued):
Sharing a sentence is not in itself a finding about the gene and the disease.
diffuse large B-cell lymphoma (33 papers, 2013 to 2026). "Subsequent pathological examination and next-generation sequencing post-surgery confirmed the diagnosis of primary seminal vesicle diffuse large B-cell lymphoma, characterized by CD79B mutation type (MCD type)." (PMID 39539541, 2024). "In the literature, MYD88 and CD79B mutations have been reported in 27/46 (58.7%) and 11/33 (33.3%) primary breast diffuse large B cell lymphomas in females." (PMID 37884941, 2023). "Mutations in EZH2 (Y646) and CD79B (Y196) were detected in 13.2% and 8% of the samples, respectively, almost exclusively in follicular lymphomas and diffuse large B-cell lymphomas." (PMID 23361872, 2013). "CD79B is an important driver of immune-privileged site-associated diffuse large B cell lymphoma." (PMID 34395276, 2021). "Recently, studies of activated B cell-like diffuse large B cell lymphoma (ABC DLBCL) have shown that mutations within the BCR subunit CD79b leads to increased BCR surface expression, suggesting that CD79b may control BCR internalization." (PMID 23372794, 2013). "Polatuzumab vedotin (Pola), an antibody–drug conjugate targeting CD79b, has reshaped frontline therapy for diffuse large B-cell lymphoma (DLBCL) through the landmark POLARIX trial." (PMID 40805213, 2025). "Polatuzumab vedotin (anti-CD79b-MMAE) has significantly improved outcomes in relapsed/refractory diffuse large B-cell lymphoma (R/R DLBCL)." (PMID 40805178, 2025). "While previous studies have shown the disruption of various cancer-associated mutations, our focus on targeting oncogenes such as PAX5, MYC, and CD79B in diffuse large B-cell lymphoma (DLBCL) represents a significant advancement." (PMID 39469218, 2024). "Recurrent mutations affecting the ITAM motifs of CD79B and CD79A (frequently seen in the activated B cell subtype [ABC subtype] of diffuse large B cell lymphoma) potentiate BCR signaling." (PMID 37954584, 2023). "The result showed 23 gene mutations, including MYD88, CD79B, CDKN2A, PIM1, RELN, PCLO, CREBBP, and so on, supporting the diagnosis of diffuse large B-cell lymphoma." (PMID 36599976, 2023). "The genetic test results of the left frontal parietal lobe lesion result revealed 23 gene mutations, including MYD88, CD79B, CDKN2A, PIM1, RELN, PCLO, CREBBP, and so on, supporting the diagnosis of diffuse large B-cell lymphoma." (PMID 36599976, 2023). "In diffuse large B-cell lymphoma (DLBCL), EZH2 and GNA13 variants are observed exclusively in the germinal center B-cell subtype, whereas CARD11, MYD88, and CD79B variants are characteristic of the activated B-cell subtype." (PMID 37601650, 2023). "Polatuzumab vedotin, an antibody-drug conjugate (ADC) targeting the B cell receptor (BCR) signaling subunit CD79B, has recently entered frontline therapy for diffuse large B cell lymphoma (DLBCL) and high-grade B cell lymphoma (HGBCL), achieving encouraging clinical results." (PMID 41668618, 2026). "Diffuse large B cell lymphoma (DLBCL), the most common and aggressive form of non-Hodgkin lymphoma, often exhibits multiple genomic aberrations, including mutations in the MYD88 and CD79B genes." (PMID 39868594, 2025). "VRL, as well as PCNSL, display typically an activated B cell-like (ABC) phenotype of diffuse large B-cell lymphoma (DLBCL), with frequent CD79B and MYD88 mutations, which may represent a strong biological rationale for the use of BTK inhibitors in the treatment of PCNSL and VRL." (PMID 33968786, 2021). "CD5+ diffuse large B-cell lymphoma (DLBCL) is a rare subtype with aggressive clinical behavior characterized by a high frequency of MYD88L265P mutations and CD79B mutations associated with persistent activation of the B-cell receptor (BCR) signaling pathway." (PMID 41341395, 2025). "Polatuzumab vedotin (Polivy) targets CD79b on B-cell tumors and was approved in 2019 for relapsed or refractory diffuse large B-cell lymphoma (DLBCL) in combination with chemotherapy." (PMID 40559642, 2025).
diffuse large B-cell lymphoma (continued). "Certain oncogenic changes in the immunotyrosine-based activation motif (ITAM) of CD79a and CD79b have been reported to occur in diffuse large B-cell lymphoma (DLBCL), which drive the segregation of the activated B-cell-like subtype." (PMID 39770542, 2024). "Polatuzumab vedotin, the first FDA-approved antibody-drug conjugate (ADC) targeting CD79b, is utilized in the treatment of previously untreated diffuse large B-cell lymphoma (DLBCL) or high-grade B-cell lymphoma (HGBL), as well as relapsed or refractory (R/R) DLBCL." (PMID 38983914, 2024). "Polatuzumab vedotin is another antibody-drug conjugate that targets the CD79b antigen expressed on lymphocytes, and it has been FDA-approved for treating R/R diffuse large B-cell lymphoma (DLBCL)." (PMID 36172151, 2022). "In 11 patients a subpopulation of CD19 CD20 CD22 CD79b-positive B lymphocytes (4%; range 1–22%), with a normal/balanced Ig kappa/lambda ratio evaluated on the CD22-positive population, was identified: 5 PCNSL, 5 diffuse large B-cell lymphoma (DLBCL), 1 follicular lymphoma." (PMID 34150651, 2021). "Polatuzumab vedotin (DCDS4501A) and pinatuzumab vedotin (DCDT2980S), MMAE-based ADCs targeting CD79b and CD22, respectively, showed clinical activity in combination with rituximab in relapsed/refractory diffuse large B-cell lymphoma (DLBCL)." (PMID 31159480, 2019).
B-cell lymphoma (24 papers, 2012 to 2026). "This study sought to determine the evolution of the mutational status of EZH2 and CD79B over time in different samples from the same patient in a cohort of B-cell NHLs, through use of a customized multiplex mutation assay." (PMID 23361872, 2013). "Mutational status of EZH2 and CD79B may vary in B-cell NHL samples over time and support the concept that individualized therapy should be based on molecular findings at the time of treatment, rather than on results obtained from previous specimens." (PMID 23361872, 2013). "The data provide a rational basis for integrating CD79B-directed ADCs with mTOR or CDK4/6 inhibitors to prevent or overcome treatment resistance of aggressive B cell lymphomas." (PMID 41668618, 2026). "CD79a and CD79b form the heterodimeric signaling component of the B-cell receptor, with CD79b being nearly universally expressed in mature B-cell lymphomas and normal B cells." (PMID 41383509, 2025). "Within our cohort of 127 cases, we noted heterogeneous surface expression of CD79b among aggressive B-cell lymphomas, with approximately 20% of cases displaying nearly exclusive intracellular positivity." (PMID 39682155, 2024). "The nearly exclusive expression of CD79b on B cells and B-cell lymphomas, coupled with its internalization upon antigen binding, has sparked a growing interest in CD79b as a therapeutic target for antibody–drug conjugates (ADCs)." (PMID 39682155, 2024). "Flow cytometry (FC) has become a valuable technique for quantifying CD79b levels on B-cell lymphoma cells in peripheral blood or bone marrow." (PMID 39682155, 2024). "The primary objective of our study was to quantitatively evaluate the surface expression of CD79b in lymph node biopsies obtained from pts with aggressive B-cell lymphomas, employing FC as an analytical tool." (PMID 39682155, 2024). "In our study focusing on CD79b expression, we examined 127 lymph node samples from pts with histological diagnosis of aggressive B-cell lymphomas; furthermore, we included 16 cases of benign reactive hyperplasia (BRH) as controls." (PMID 39682155, 2024). "Other promising B-cell markers in the therapeutic context are CD79B, expressed in more than 90% of B-cell lymphomas, CD30, CD37, and CD70." (PMID 39518937, 2024). "The chief advantage of ADCs over small-molecule-based therapeutics is that ADCs specifically target only their surface antigens, such as CD19, CD22, CD79b, etc., in B-cell lymphomas." (PMID 39518937, 2024). "We found that LBCLs exhibited lower and heterogeneous CD79b expression, with 18% of cases showing almost exclusively intracellular positivity and, in particular, low surface expression in primary mediastinal B-cell lymphomas." (PMID 39682155, 2024). "CD79b, a B-cell-specific antigen recently targeted for therapy in aggressive B-cell lymphomas, exhibits widespread expression on mature B-cell-derived lymphomas, as evidenced by immunohistochemical studies." (PMID 39682155, 2024). "Zanubrutinib is a BTK inhibitor reported to be effective for B‐cell lymphomas with MYD88 and CD79b mutations, double expression of MYC and BCL2/BCL6, and CD5 expression." (PMID 39054569, 2024). "Examination of alterations in key pathways implicated in B-cell lymphomas suggests involvement in chromatin remodelling (CREBBP and EP300) and regulators of NF-κB signalling (TNFAIP3, BCL10, MYD88, CD79B and CARD11) were affected." (PMID 39460552, 2024). "CD79b, a B-cell-specific antigen, is highly expressed in mature B-cell lymphomas, making it a promising therapeutic target." (PMID 39682155, 2024). "Mosunetuzumab is also being evaluated in a phase 1b/2 study (NCT03671018) in combination with polatuzumab vedotin, a CD79b antibody–drug conjugate, in patients with R/R B-cell lymphoma." (PMID 36959808, 2023). "Expressed on the surface of over 90% B cell lymphomas, CD79B is a valid target to selectively deliver payloads to B cell lymphomas." (PMID 36654819, 2022).
B-cell lymphoma (continued). "Several novel immunotherapies, including autologous anti‐CD19 chimeric antigen receptor (CAR) T‐cell therapy, anti‐CD20 × anti‐CD3 bispecific antibody, and CD79b‐targeted antibody‐drug conjugate, have been studied for the treatment of rel/ref B‐cell lymphoma." (PMID 34105893, 2021). "CD79B is a receptor important in B cell development that is expressed in several subtypes of B cell NHL, including MCL." (PMID 32552760, 2020). "It has to be explored whether this mechanism could also contribute to reduced CD79b surface expression in aggressive B-cell lymphomas." (PMID 39682155, 2024). "The CD79b-targeted antibody–drug conjugate polatuzumab vedotin (pola), alone and with chemoimmunotherapy, has clinical efficacy and a tolerable safety profile in B-cell non-Hodgkin lymphoma (B-NHL)." (PMID 32770353, 2020). "BACKGROUND: Numerous genomic abnormalities in B-cell non-Hodgkin lymphomas (NHLs) have been revealed by novel high-throughput technologies, including recurrent mutations in EZH2 (enhancer of zeste homolog 2) and CD79B (B cell antigen receptor complex-associated protein beta chain) genes." (PMID 23361872, 2013). "The clinical significance of CD79b extends beyond CD79b-ADC therapies, with its potential as a target for CAR-T cell therapy in B-cell lymphomas gaining interest." (PMID 39682155, 2024). "Both the percentage of CD79b expression and CD79b-MFI were found to be lower in aggressive B-cell lymphoma cases compared to a control group of BRH." (PMID 39682155, 2024). "In our examination of the different histological subtypes of aggressive B-cell lymphomas, PMBCL stood out with significantly lower surface CD79b expression compared to others (median 0.8% IQR 0–48.5 vs. 80% IQR 24–97, respectively, p = 0.0005)." (PMID 39682155, 2024). "However, MYC-driven B cell lymphomas, particularly HGBCL with MYC and BCL2 rearrangements, frequently silence surface BCR/CD79B expression, limiting the therapeutic reach of CD79B-directed ADCs and underscoring the need for complementary treatment strategies." (PMID 41668618, 2026). "One of the strengths of our WM scoring system is that it relies on antigen markers that are routinely used and widely available in haematology laboratories performing MFC analysis for B‐cell lymphomas (CD19, CD79b, CD22, FMC7 and CD27) and myeloid neoplasms (CD13)." (PMID 40407640, 2025). "No variations in CD79b expression were observed considering expression levels of other B-cell lymphoma markers, such as CD10, CD5, CD19, and CD20." (PMID 39682155, 2024). "Neutropenia is more consistently observed in ADCs that contain a MMAE payload, including brentuximab vedotin, and was recently identified as a key toxicity of polatuzumab vedotin, a CD79b-targeting ADC, as part of a dose-escalation study in B-cell NHL patients." (PMID 29453628, 2018).
CNS lymphomas (15 papers, 2022 to 2025). "Of the 12TexSig, recurrent mutations of CD79B have been reported as the hallmark of primary central nervous system lymphomas." (PMID 37635346, 2023). "The prognostic impact of MYD88 and CD79B mutations vanished if CNS lymphomas were excluded (p = 0.2 and 0.6, respectively)." (PMID 36051079, 2022). "Gain-of-function mutations in CD79B often coexist with MYD88 mutations in extranodal lymphomas, such as primary central nervous system lymphoma (PCNSL) and primary testicular lymphoma (PTL)." (PMID 40299829, 2025). "We present the case of a patient with primary CNS lymphoma (PCNSL), with MYD88 and CD79B gene variants, who was unable to complete standard induction and consolidation treatment due to toxicity and co-morbidities after three cycles of MATRix." (PMID 41226558, 2025). "Lastly, primary central nervous system lymphoma (PCNSL) is an aggressive large B-cell lymphoma that also displays CDKN2A loss and mutations in MYD88, CD79B, and TBL1XR1, thus with potentially definable genetic subtypes." (PMID 40191738, 2024). "Primary CNS lymphoma (PCNSL) and PVRL are closely related diseases and share many genetic alterations like mutations in myeloid-derived factor 88 (MYD88) and CD79B leading to NF-κB pathway activation and homozygous loss of CDKN2A resulting in genomic instability." (PMID 38671086, 2024). "Accordingly, the genetic profile is dominated by NFκB-activating mutations, predominantly in MYD88 and CD79B, which are enriched in ABC-DLBCL and, especially, primary central nervous system lymphoma (PCNSL), primary testicular lymphoma (PTL), and intravascular large B-cell lymphoma." (PMID 35028710, 2022). "Moreover, MYD88, CD79B, and PIM1 mutations were commonly found in primary CNS lymphomas and DLBCLs with CNS relapse." (PMID 36081566, 2022). "Recurrent mutations in the JAK–STAT, NF-κB, and B-cell receptor (BCR) pathways, including CD79B, MYD88, and CDKN2A deletions, have been identified as the defining characteristics of primary central nervous system lymphomas." (PMID 40538656, 2025).
autoimmune disease (6 papers, 2019 to 2025). A disorder resulting from loss of function or tissue destruction of an organ or multiple organs, arising from humoral or cellular immune responses of the individual to their own tissue constituents. "Moreover, anti-CD79b antibody could induce the cell-free immune response of B cells to resist autoimmune diseases." (PMID 37525657, 2023). "Furthermore, we identify several associations of autoimmune diseases with proteins in the immune pathway including inflammatory bowel disease with T-cell surface glycoprotein (CD1C) and rheumatoid arthritis with B-cell antigen receptor complex-associated protein beta chain (CD79B)." (PMID 37550624, 2023).
leukemia (6 papers, 2018 to 2024). A malignant (clonal) hematologic disorder, involving hematopoietic stem cells and characterized by the presence of primitive or atypical myeloid or lymphoid cells in the bone marrow and the blood. "For example, CD79B has been associated with reduced survival, and is considered a suitable immunotherapeutic target for leukemia and lymphoma." (PMID 30796273, 2019). "ELISA results indicated that anti-CD79B-scFv binds to Ph+ leukemia cell lines in a concentration-dependent manner." (PMID 38741123, 2024). "Due to small size and the versatility for different conjugations, single-chain fragment variable (scFv) region of anti-CD79B monoclonal antibody was chosen for the binding with CD79B on the surface of Ph+ leukemia cell lines." (PMID 38741123, 2024). "This study also identified immune disease-related genes associated with somatic mutations such as MYD88 and BCL10 in NF-κB signaling, CD79B, PAX5, and BCR in B-cell development, and MYH11, RUNX1, and TET2 in leukemia." (PMID 29937999, 2018). "Thus, it is highly possible to utilize CD79B as an antigen for targeting Ph+ leukemia by its corresponding scFv." (PMID 38741123, 2024). "Subsequently, the expression of CD79B protein in Ph+ leukemia cell lines was confirmed by Western blotting, and higher expression levels of CD79B in Ph+ leukemia cell lines were further verified by the comparison with human bone marrow stromal cell line of HS-5." (PMID 38741123, 2024). "Moreover, the CD79b-ADC PolVed significantly diminished overall leukemia burden and prolonged mouse survival in sCD79b+ BCP-ALL-PDX models of different cytogenetic backgrounds." (PMID 35935606, 2022). "Therefore, CD79B was selected in this study as a surface molecule to specifically bind the scFv portion of its antibody, which should be able to result in targeted therapy for Ph+ leukemia." (PMID 38741123, 2024). "As immune disease-related genes, MYD88 (81.4%) and BCL10 (25.9%) in NF-ĸB signaling, CD79B (59.2%), PAX5 (22.2%), and BCR (7.4%) in B-cell development, and MYH11 (25.9%), RUNX1 (7.4%), and TET2 (7.4%) in leukemia were observed." (PMID 29937999, 2018).
multiple myeloma (6 papers, 2017 to 2024). "CD79b is expressed in early B cell development and is only lost in the late plasma cell stage, although it is found in some myelomas." (PMID 37296844, 2023). "SMM patients with an evolving pattern of the M-protein showed an increase in genes associated to myeloma (SLAMF7, CD79A, CD79B) and AXL." (PMID 34880879, 2021). "In this context, some opportunities for development could be exploited like targeting CD79b in multiple myeloma." (PMID 37740463, 2023). "Furthermore, the modular DVD platform was used to prepare potent and specific ADCs targeting CD138 and CD79B, two clinically established targets overexpressed in multiple myeloma and non-Hodgkin lymphoma, respectively." (PMID 29062027, 2017). "Targets expressed in normal bone marrow plasma cells can be divided in those in which expression in myeloma cells remains stable in later stages in longitudinal samples (i.e., CD38, CS1, BCMA, FCRH5, CD74, CD79B), and those for which expression is stage-dependently lost (e.g., CD19, CD22, BAFF-R)." (PMID 38035078, 2023).
Burkitt lymphoma (5 papers, 2018 to 2021). A rare form of malignant mature B-cell non-Hodgkin lymphoma. "One study detected the expression of CD79b on patients with different types of B-cell malignancies including DLBCL, Burkitt lymphoma, FL, and evaluated the efficacy of anti-CD79b CAR-T cells in vitro and in vivo." (PMID 34256851, 2021). "By contrast, CD19 and CD79b are absent in KIS-1 cells but are expressed in GM12878 (an Epstein-Barr Virus-transformed B lymphocyte), RAJI (Burkitt lymphoma) and Nalm-6 (Acute Lymphoblastic Leukemia) cells." (PMID 33452395, 2021).
chronic lymphocytic leukemia (5 papers, 2016 to 2024). "The under-expression of CD81, CD79b, and positive CD43 and ROR1 expression, noted in the DURAClone CLB panel specifically assists in distinguishing B-cell CLL from mantle cell lymphoma and other CD5 negative B-cell LPDs." (PMID 36483322, 2022). "The expression of CD79b varies among B cell neoplasms, being virtually absent in B-acute lymphoblastic leukemia (B-ALL) but widely expressed in mature B cell neoplasms, except for chronic lymphocytic leukemia (CLL)." (PMID 38927948, 2024).